EP300 (EP300 lysine acetyltransferase)
Diseases named in the same sentence as EP300 in open-access papers (continued):
Sharing a sentence is not in itself a finding about the gene and the disease.
tumor (continued). "However, some literatures also suggested EP300 as a tumor-promoter in several malignancies." (PMID 32943995, 2020). "In our study, the tumor with the EP300 D1399N mutation had increased Myc expression (data not shown), suggesting that this particular EP300 mutation may also play a role in Myc-related oncogenesis similar to K27M mutagenesis." (PMID 29084603, 2017). "Proteomic profiling further revealed its impact on multiple oncogenic and tumor-suppressive proteins, with notable upregulation of SERPINB2, KIT, and NOTCH1, alongside downregulation of COX2, DNMT1, MAPK1, AKT1, MKI67, EP300, and SMC1A." (PMID 41321870, 2025). "This creates a positive feedback loop involving EP300, CMTM6, IGF2BP1, and EP300 (mRNA), which strengthens tumor stemness and promotes drug resistance in PDAC." (PMID 40356985, 2025). "This loop reinforces tumor stemness by stabilizing MYC and EP300 mRNAs via IGF2BP1‐mediated m6A modification." (PMID 39488785, 2024). "Here, we discover that targeting EP300/CBP using the domain-specific inhibitors, A485 (HAT) or CCS1477 (BRD) have different effects in select tumor types." (PMID 38664416, 2024). "Then, we assessed the significance of EP300 for the prognosis of LUAD by conducting Cox regression analysis of covariates, including gender, age, tumor size, tumor grade, T and N staging, and expression of PDL1, ALK, EGFR, and EP300." (PMID 38256128, 2024). "Oncogenes (e.g., NOTCH1 and ERBB2) tended to increase in centrality in tumor modules while tumor suppressors (e.g., BAP1, AKT1, and EP300) decreased in centrality." (PMID 38685127, 2024). "The m6A reader IGF2BP1 stabilizes the EP300 and MYC mRNAs by recognizing m6A modifications, forming a positive feedback loop that enhances tumor stemness and ultimately contributes to PDAC resistance." (PMID 39488785, 2024). "The two most frequently occurring gene pairs were observed in three tumor types, EPHA2-ATM and EP300-ATM gene pairs." (PMID 39160568, 2024). "With tumor tissues obtained from the models above, we performed metabolomics targeting energy metabolism using mice LUAD models from EP300-KO and WT tumor tissues." (PMID 38256128, 2024). "Among them, the target genes of H3K4me3 resulting from FOXA1, GATA3 and PLOR2A as well as H3K27ac resulting from EP300 and GATA3 were significantly enriched in the gene sets (CERES = −2∼−0.4, p < 0.001), signifying a broad dependency for tumor proliferation." (PMID 37876590, 2023). "CN470 has notable anti-tumor activity against MLL1-rearranged ALL by binding to the bromodomains (BRDs) of BRD4, CREBBP, and EP300 in vitro and in vivo." (PMID 36831561, 2023). "Inhibition of CREBBP/EP300 with GNE-781 impairs the differentiation of human CD4+ T-cells into Tregs, providing a therapeutic approach by promoting a pro-inflammatory tumor microenvironment." (PMID 36831561, 2023). "CNS tumors with EP300::BCOR fusion seem to be distinct from their BCOR ITD counterparts in terms of age, location, progression-free survival, tumor growth pattern, and immunopositivity for the BCOR protein." (PMID 36782314, 2023). "First, examination of our RNA-sequencing data revealed that of the 14 known HATs, the EP300 (KAT3B) and KAT2B transcripts showed uniformly enhanced expression in radiated tumor cells at both 2 and 7-days post-treatment." (PMID 36261421, 2022).
tumor (continued). "Here we use CPI-1612 to demonstrate that inhibition of CREBBP/EP300 HAT activity represents a promising strategy to suppress ER-mediated proliferation and tumor growth." (PMID 35353838, 2022). "Epigenetic alterations relating to histone methylation (KMT2D, KMT2C, EZH2), histone acetylation (CREBBP, EP300), and DNA methylation (TET2) play an important role in tumor progression for FL and DLBCL." (PMID 36497332, 2022). "The correlation analysis revealed significant positive correlations were observed between EP300 and KIF11 in various tumor types." (PMID 33613109, 2021). "EP300 and its cofactor CREBBP are reported to display oncogene or tumor suppressive functions depending on the malignancy considered." (PMID 34439123, 2021). "Surprisingly, clusters with the strongest oncogenic and tumour suppressor potential share five regulatory regions (MAX, ERG, EP300, AR and MYC)." (PMID 34198662, 2021). "Similar to H3K27ac and H3K4me3 signal, EP300 and WDR5 were also significantly enriched in circSOD2 promoter from HCC tumor tissues compared to normal liver tissues." (PMID 33234142, 2020). "We show that knockdown of EP300 abrogates the CSC phenotype of TNBC cells and reduces tumor growth and metastasis." (PMID 33167919, 2020). "We demonstrated that knockdown of EP300 reduced the expression of ABCG2, eliminated side population cells and decreased tumor initiating as well as metastatic potential." (PMID 33167919, 2020). "Compared to the normal liver tissues, 278 acetylation sites in 189 proteins were down-regulated while three acetylation sites in three proteins (EP300, GRHPR, and GLDC) were up-regulated with significant differences in tumor tissues." (PMID 33093847, 2020). "EP300 KD abolished the CSC phenotype by reducing ABCG2 expression, side population cells and tumorsphere formation capacity in vitro as well as tumor formation in a xenograft mouse model in vivo." (PMID 33167919, 2020). "Given the critical importance of EP300/CBP for gene expression, understanding their regulation by the metabolic context during tumor evolution is a key issue." (PMID 32603375, 2020). "These more frequently mutated instances encompassed in total 53 genes and included the experimentally characterized hotspots within the PTEN, FBXW7, SMAD4, EP300, and CREBBP tumor suppressors." (PMID 29572294, 2018). "Genes such as CFLAR, EP300, GBP2, HEYL, KLF7, NOTCH1 or POFUT showed a similar correlation with NUMB or NUMBL in the three tumor types considered." (PMID 29507685, 2018). "While some of the mutations are oncogenic (i.e., IDH1/2, EZH2, and DNMT3A), others are tumor suppressive (i.e., KDM6A, CREBBP/EP300, and SMARCB1)." (PMID 27999365, 2016). "In the “waves” pattern CESC, the first wave genes EP300, MLL2, and MLL3 were all tumor suppressor genes, and the second wave genes FBXW7 and ATRX were also tumor suppressor genes." (PMID 26992457, 2016). "We identified newly emerging mutations in genes that were not covered by our targeted NGS panel such as ATM, NOTCH2, EP300, ARID1A and MAP3K1 and also noticed an increase in tumor mutational burden (TMB) in some cases during progression." (PMID 40973765, 2025). "Interestingly, the data from both the GSE94660 and GSE121248 datasets revealed upregulation of EP300 and MCM8 in HBV‐positive HCC tumors compared to non‐tumor tissues (LogFC > 0)." (PMID 40095759, 2025). "They likely selectively block abnormal acetylation processes within the tumor microenvironment without broadly inhibiting EP300 essential functions in physiological immune responses." (PMID 41562074, 2025). "Moreover, several epigenetic-related genes such as ARID1A, EP300, and CREBBP were also identified, highlighting the functional role of epigenetic modulation during tumor progression." (PMID 39334392, 2024). "The influence of RBM15 may be mediated via the EP300/CBP‐RBM15‐CXCL11 axis, highlighting its potential role in tumour biology." (PMID 39580709, 2024).
tumor (continued). "Clinical analysis of this research discovered a correlation between EP300 expression and advanced tumor stage in LUAD, suggesting EP300 could be an independent prognostic factor for individuals with LUAD." (PMID 38256128, 2024). "Therefore, these elegant approaches determined that culture stiffness influences EP300’s role as a mechanosensitive molecule mediating mechanotransduction of HSC activation, tumorigenesis, and tumor progression." (PMID 37569677, 2023). "The newly transcribed LncRNA PACERR interacts directly with CTCF, forming the CTCF/PACERR complex to recruit HAT EP300, resulting in increased chromatin accessibility and transcriptional activation of PTGS2, the critical driver of M2 polarization and pro‐tumour functions in TAMs." (PMID 35184402, 2022). "Notably, while some of the targets revealed by our analysis (such as IGF1R, HGF, and KAT6A), are well-characterized drivers of tumorigenesis, others are known tumor suppressors e.g., PTEN, EP300." (PMID 35347083, 2022). "Inhibition of bromodomain reduces tumor growth, suggesting that the CBP/EP300 bromodomain may be targeted to enhance antitumor immunity." (PMID 35244291, 2022). "Conditional deletion of EP300, a highly connected protein interactor in both the GWAS-FI (exhibiting 16 interactions) and SMR-FI network (exhibiting 9 interactions), results in impaired TReg suppressive function and reduced tumour growth." (PMID 33549134, 2021). "Similar to the previous reporting the driver genes in CC, FBXW7, EP300, CASP8 and FAT1(10%, 20%, 10% and 10% of tumor, respectively) were also identified in our cohort with a low frequency, which may result from a small sample size in our cohort." (PMID 34221990, 2021). "Since we used an immunocompromised (NSG) mouse model, immunological factors are unlikely to play a role in the absence of in vivo tumor formation through EP300 KD." (PMID 33167919, 2020). "Taken together, the data showed that EP300 KD inhibited tumor initiation/growth in vivo but did not affect the growth behavior of KD cells in vitro even under conditions partially mimicking in vivo condition." (PMID 33167919, 2020). "In details, the decrease of FGF2, FLT1, CCL2 mRNA, along with increase of SERPINF1 mRNA were observed in EP300 knockdown ESCC cells, predicting that EP300 may promote tumor initiation via angiogenesis in ESCC." (PMID 31632486, 2019). "Further western blot analysis also confirmed the expression change of these EMT related markers in EP300 knockdown ESCC cells, indicating that EP300 may promote tumor progress via EMT in ESCC." (PMID 31632486, 2019). "We demonstrate the clinical relevance of these results by validating that expression of EP300 is prognostic, predicting survival independent of age at diagnosis and tumor grade." (PMID 21489305, 2011). "The cMS repeats in CREBBP and EP300 are short and unlikely to be mutated in a high proportion of MSI-High tumours." (PMID 21209843, 2010). "Additionally, EP300, a histone acetyltransferase, was found to interact with CEBPB, suggesting a cooperative mechanism that amplifies CEBPB-driven transcriptional activation of tumor-promoting and immune-related genes." (PMID 40949418, 2025). "Indeed, CEBPB and EP300, along with genes related to the Mitogen-Activated Protein Kinase (MAPK) signaling cascade such as MAP3K1, MAP2K2, and MAP3K11 were significantly upregulated in RMC tumor cells following treatment with nivolumab plus ipilimumab." (PMID 41290625, 2025). "Copy-number gains of EP300 and SOX10 were found to correlate with higher gene expression levels, suggesting that these copy-number gains have a functional consequence and may thus be biologically relevant in tumor samples." (PMID 38994683, 2024).
tumor (continued). "Thus, the metabolic context (i.e., capacity to store glycogen) may define whether glucose inhibits AMPK, acting as tumor suppressor at initial tumor stages, or induces AMPK acting as tumor promoter at advanced stages to drive EP300/β-catenin interactions." (PMID 32603375, 2020). "Moreover, other fusions involving BCPs genes, such as EP300 fusion with ZNF384, ASH1L fusion with C1ORF61, SMARCA4 fusion with CARM1, MLL fusion with AF4, AF9, or AF10 are also found in tumors such as hematological malignancies, breast cancers, glioblastomas, driving tumor progression." (PMID 37142850, 2023). "However, only EP300 and not CREBBP was significantly upregulated in RMC tumor cells of patients treated with ICT, suggesting that p300 is specifically engaged during RMC hyperprogression." (PMID 41290625, 2025). "Importantly, similarly to what was seen in EP300 knockouts, ETC-159 treatment only minimally slowed down the GATA6-knockout tumor growth without reaching statistical significance, confirming that downregulating GATA6 conferred resistance to PORCN inhibition." (PMID 35536676, 2022).
infection (47 papers, 2011 to 2026). The state of being infected such as from the introduction of a foreign agent such as serum, vaccine, antigenic substance or organism. "Looking back at these patients with EP300 mutations, we found that a history of recurrent infection or even primary low immunity is a notable feature of the disorder." (PMID 36797748, 2023). "Genetic depletion of either KMT2D or EP300 decreased icSARS-CoV-2-mNG infection in Huh7.5 and Vero E6 cells as measured by mNeonGreen." (PMID 37410700, 2023). "Infection of K562 cells with lentiviruses expressing shRNAs against EP300 or CREBBP or both reduced the expression of the targeted proteins." (PMID 29884215, 2018). "In this sense, our results show a PPI with EP300, which involves the p300/CBP complex, one of the best-characterized cofactors of NF-kB and binds specifically to RELA59, validating the possible importance of this system in infection with SARS-CoV2." (PMID 34031419, 2021). "Our transcriptome analyses indicated that the expression of EP300 was not significantly changed by the SFVmfu infection (data not shown)." (PMID 31969530, 2020). "We found that those CRISPR-targeted cells with decreased ACE2 expression (SMAD4, EP300, and PIAS1) also exhibited a decrease in both the proportion of infected cells by SARS-CoV-2 nucleocapsid protein immunofluorescence and in viral infectivity by TCID50 at 48 hours post-infection." (PMID 35231079, 2022). "Notably, E2 proteins interact with CREBBP/EP300 and this could enhance the formation and development of PEB-BLOCs in a natural infection." (PMID 24832099, 2014).
hematological malignancies (25 papers, 2015 to 2025). "CREBBP/EP300 gene mutations frequently occur in hematological malignancies through a variety of different mechanisms, resulting in poor patient prognosis, including worse overall survival (OS), progression-free survival (PFS), and event-free survival (EFS)." (PMID 36831561, 2023). "It is instructive to design personalized immunotherapy for hematological malignancies with CREBBP/EP300 driver mutations using next-generation sequencing technologies." (PMID 36831561, 2023). "Genetic abnormalities of CREBBP/EP300 are frequent in hematological malignancies and include gene mutations, copy number variations, and structural variations." (PMID 36831561, 2023). "Aberrant CREBBP/EP300 expression is common in hematological malignancies and is associated with chemoresistance." (PMID 36831561, 2023). "Both CREBBP and EP300 sequence mutations have been reported in solid tumors and, more recently, also in hematological malignancies, whereas rare EP300 mutations have been detected in some ALL cell lines." (PMID 26543507, 2015). "However, a growing number of studies have shown that aberrant expression of CREBBP/EP300 is associated with tumorigenesis and the progression of hematological malignancies." (PMID 36831561, 2023). "The reviewed information revealed that genetic aberrations of CREBBP/EP300 were observed in various types of solid tumors and hematologic malignancies and considered promising therapeutic targets." (PMID 40558049, 2025). "In this review, we summarize the role of CREBBP/EP300 in normal hematopoiesis and highlight the pathogenic mechanisms of CREBBP/EP300 in hematological malignancies." (PMID 36831561, 2023). "Here, this review discusses the critical role of CREBBP/EP300 in normal hematopoiesis and also provides a comprehensive overview of how they contribute to the genesis and progression of hematologic malignancies." (PMID 36831561, 2023). "As key acetyltransferase family members and transcriptional co-activators, CREBBP/EP300 regulate the acetylation levels of multiple substrates involved in the regulation of normal hematopoietic maintenance and the development of hematological malignancies." (PMID 36831561, 2023). "Genetic aberrations of CREBBP/EP300 have been observed in various types of solid tumors and hematologic malignancies, making them serve as promising therapeutic targets." (PMID 36831561, 2023). "To date, there is sufficient evidence that HDACis or other inhibitors of epigenetic modification molecules, alone or in combination, are effective against some hematologic malignancies with aberrant CREBBP/EP300 expression." (PMID 36831561, 2023). "Currently, CREBBP/EP300 are attractive targets for drug development and are increasingly used as favorable tools in preclinical studies of hematological malignancies." (PMID 36831561, 2023). "Transcriptional or epigenetic dysregulation of CREBBP/EP300 in hematological malignancies may lead to chemoresistance." (PMID 36831561, 2023). "Finally, we discuss some prospective therapeutic strategies for CREBBP/EP300 inhibitors in hematological malignancies." (PMID 36831561, 2023). "In this review, we focus on summarizing several representative CREBBP/EP300 BRD inhibitors (CCS1477, CPI-637, and GNE272, etc.)and HAT inhibitors (A485, A-241, and C646, etc.)and their functions in hematological malignancies." (PMID 36831561, 2023). "Here, after providing a brief overview of the molecular characteristics and functions of CREBBP/EP300, we summarize the current knowledge about the implications of CREBBP/EP300 in normal hematopoiesis and hematological malignancies." (PMID 36831561, 2023).
hematological cancers (7 papers, 2012 to 2025). "Our study shows that several hematologic cancer cell lines are sensitive to inactivation of CREBBP/EP300 bromodomains." (PMID 29884215, 2018). "Further experiments will be needed to better investigate the role of CBP/EP300 as a regulator of MICA gene expression in patient-derived MM cells and in other hematological tumors." (PMID 27903272, 2016). "For example, aberrant formation of fusion proteins through chromosomal translocations of HATs such as E1A-binding protein p300 (EP300), nuclear receptor coactivator-2 (NCOA2), MYST3 [histone acetyltransferase (monocytic leukemia) 3] and MYST4 have been identified in hematological cancers." (PMID 23162793, 2012).